LBP (lipopolysaccharide binding protein)
Diseases named in the same sentence as LBP in open-access papers (continued):
Sharing a sentence is not in itself a finding about the gene and the disease.
type 2 diabetes (17 papers, 2016 to 2025). "This study clearly demonstrated that serum LBP levels are independently and positively associated with arterial stiffness in patients with type 2 diabetes." (PMID 28486964, 2017). "Further studies measuring various parameters of gut integrity, such as occludin, claudins, or mucin, in addition to LBP and zonulin, are necessary to determine the impact of brown seaweed and their extracts on gut integrity among people at risk of type 2 diabetes." (PMID 35323474, 2022). "Additionally, a foregoing study reported that the rs2232592 polymorphism, located in the intron of LBP, was significantly related to type 2 diabetes." (PMID 35005033, 2021). "The gut microbiota and gut permeability, as assessed through circulating lipopolysaccharide binding protein (LBP), may underlie the link between chronic inflammation and type 2 diabetes (T2D)." (PMID 36687728, 2022). "The levels of LPS and LBP are significantly higher in the serum of obese individuals and patients with type 2 diabetes than in controls, respectively." (PMID 31810329, 2019). "This study clearly demonstrated that serum LBP levels are independently and positively associated with aortic PWV in patients with type 2 diabetes." (PMID 28486964, 2017). "This study indicates a potential role of the LPS/LBP-induced innate immunity in the development and progression of arterial stiffness in type 2 diabetes." (PMID 28486964, 2017). "The present study demonstrated that serum LBP levels are positively associated with arterial stiffness, as assessed by aortic PWV, in patients with type 2 diabetes." (PMID 28486964, 2017). "Therefore, in the present study, we investigated the association between serum LBP levels and arterial stiffness by measuring aortic pulse wave velocity (PWV) in patients with type 2 diabetes." (PMID 28486964, 2017). "In light of the combined experimental and clinical evidence, and considering the fact that circulating LBP binds to LPS and promotes the innate immune response, our data may indicate a critical role of the LPS/LBP-induced inflammation in the pathogenesis of arterial stiffness in type 2 diabetes." (PMID 28486964, 2017). "In the heat, individuals with type 2 diabetes had greater postexercise increases in IFABP [+545 pg/mL (95% confidence interval: 222, 869)] and LBP [+3.64 μg/mL (1.73, 5.56)] relative to healthy control subjects (p < 0.048), but these resolved after recovery." (PMID 40159416, 2025). "In a previous case-control study, we reported that gut dysbiosis, a high detection rate of live bacteria in blood, and elevated plasma LBP levels occurred in Japanese patients with type 2 diabetes mellitus (T2DM) but not in those without T2DM." (PMID 31536546, 2019).
liver fibrosis (15 papers, 2012 to 2025). "As LBP is produced by hepatocytes one would expect that changes of LBP synthesis would occur with progressed liver fibrosis." (PMID 25785448, 2015). "Briefly, the levels of LBP and sCD14 were determined in patients with varying levels of liver fibrosis through the use of a commercially available anti-sCD14 and LBP ELISA kits." (PMID 23750224, 2013). "We have done this through the measurements of markers of endotoxin exposure such as soluble CD14 (sCD14) and LPS binding protein (LBP) in patients with varying levels of liver fibrosis." (PMID 23750224, 2013). "Mice with deficiencies in components of TLR4 signaling pathway, CD14, LPS binding protein (LBP), or TLR4 have impaired TLR signaling and are less susceptible to liver fibrosis." (PMID 22973518, 2012). "Another study of 237 MASLD patients revealed that LBP was associated with NASH severity and liver fibrosis, with higher LBP linked to inflammation, fibrosis, and the TM6SF2 rs58542926 T allele—a genetic variant associated with impaired lipid metabolism and increased MASLD/NASH risk." (PMID 40410852, 2025). "A lower degree of liver fibrosis was documented in studies of carbon tetrachloride- or bile duct ligation-induced liver fibrosis in TLR4-mutant mice along with mutations in MyD88, CD14, TRIF and LBP." (PMID 39201329, 2024). "Given the pivotal role of the TGF-β/Smad pathway in liver fibrosis induced by LBP, this study investigated whether targeting LBP or the TGF-β/Smad pathway could effectively prevent and treat GC-LM." (PMID 37789385, 2023). "Microbial components including lipopolysaccharide (LPS), lipoteichoic acid, and flagellin may promote liver fibrosis by the stimulation of HSCs and Kupffer cells with a LPS binding protein (LBP) and soluble CD14 (sCD14)." (PMID 33348839, 2020). "Serum LBP was shown to associate with hs-CRP, NALFD, and NAFLD with liver fibrosis." (PMID 30458048, 2018). "LPS has been shown to accelerate liver fibrosis through engagement of TLR-4 on hepatocytes and HSC following membrane binding via LPS-binding protein (LBP) and CD14." (PMID 24865485, 2014). "Moreover, LBP is an acute-phase protein that binds to lipopolysaccharide to induce the downstream TLR-4 signaling pathways of innate immunity and the inflammatory pathway of NASH, liver fibrosis and metabolic related diseases." (PMID 30458048, 2018). "A positive correlation is found between the change of serum LBP levels and the change in hs-CRP and NFS, implying LBP is not only a metainflammatroy biomarker, but might also be a potential biomarker like NFS as a non-invasive test for the evaluation of liver fibrosis in NAFLD." (PMID 30458048, 2018).
liver disease (12 papers, 2008 to 2025). "Furthermore, the presence of elevated LBP levels in smokers indicates increased bacterial translocation, which has been previously linked to hepatic fibrogenesis and liver disease progression in ACLD." (PMID 40899194, 2025). "Because the liver is an important organ of blood circulation, translocated LPS and LPS binding protein (LBP) eventually enter the liver, leading to liver disease." (PMID 35754546, 2022). "Probiotics have a beneficial effect on liver disease, Lactobacillus casei reduces plasma levels of LPS-binding protein (LBP)." (PMID 36233804, 2022). "In our cohort, PV‐1 was associated with the severity of liver disease, that is, compensation/decompensation status, albumin, platelet count, INR and bilirubin, but also with inflammatory markers such as WBC count and the acute phase proteins CRP and LBP." (PMID 40317887, 2025). "However, when we compared LPS levels (as well as LBP and sCD14 levels) between bariatric patients with limited liver disease to patients with NASH/NASH and fibrosis we found that LPS levels were similar between the subgroups." (PMID 27992443, 2016). "In this series of AUD patients with no decompensated liver disease admitted for hospital treatment of the disorder, plasma marker levels consistent with increased monocyte activation and increased systemic inflammation were associated with the presence of ALF, as were higher LBP levels." (PMID 34441792, 2021).
coronary artery disease (11 papers, 2015 to 2025). "The most enriched proteins in ICM are serum amyloid A1, lipopolysaccharide-binding protein, and activated protein C, which are biomarkers associated with coronary artery disease." (PMID 38259301, 2023). "LPS, LBP and sCD14 have been linked to the pathogenesis of coronary artery disease and HF." (PMID 40920777, 2025). "Given the role of inflammatory activation by TLR4 in atherogenesis, our finding of LBP in human coronary artery plaques in vivo, and plaque-derived systemic release of LBP are novel findings that justify further consideration of LBP as a pathogenic factor in coronary artery disease." (PMID 28642677, 2017). "Higher levels of circulating LBP have been observed in cirrhosis of the liver and in other conditions such as coronary heart disease, diabetes, and inflammatory bowel disease." (PMID 39997462, 2025). "Lipopolysaccharide-binding protein (LBP)levels have been found to besignificantly higher in coronary artery disease (CAD) patients and was shown to be an independentlybiomarker for total and CVD related mortality." (PMID 39076735, 2023). "A second study reported mean LBP concentrations of 20.6 and 17.1 pg/mL for patients with and without angiographically confirmed coronary artery disease." (PMID 39997462, 2025). "Two previous studies showed that serum LBP levels were a significant predictor of prevalent coronary artery disease and cardiovascular mortality, independent of established cardiovascular risk factors and inflammatory markers, in hospital-based cohort studies." (PMID 28486964, 2017). "Furthermore, serum LBP levels were shown to be a predictor of prevalent coronary artery disease and cardiovascular mortality, independent of established cardiovascular risk factors and markers of systemic inflammation." (PMID 28486964, 2017).
mastitis (11 papers, 2008 to 2021). Inflammation of breast tissue during lactation or postpartum due to an obstructed duct or infection. "The significant changes in expression of LBP, TLR, CH3L1 and CD14 during the early stages of infection make them suitable candidates for early infection diagnostic biomarkers for sub-clinical mastitis." (PMID 32518370, 2020). "Another potent APP, lipopolysaccharide-binding protein (LBP) which is a liver-derived acute phase protein, has also been reported to show increased concentration in milk during bovine mastitis compared with normal conditions." (PMID 31750312, 2019). "LBP has also been shown to be induced by S. aureus in an experimental intramammary infection during clinical mastitis." (PMID 29121106, 2017). "Many of the genes within this category have previously been identified as being involved in the immune response to mastitis, including LBP, STAT3, S100A8 and SOD2." (PMID 23324411, 2013). "Acute phase proteins haptoglobin (Hp), serum amyloid A (SAA) and lipopolysaccharide binding protein (LBP) have suggested to be suitable inflammatory markers for bovine mastitis." (PMID 18554387, 2008). "The possible mechanism of Paeoniae Radix Alba in treating mastitis might be that paeoniflorin inhibits the expression of LBP and antagonize LBP-mediated LPS inflammatory response." (PMID 30911319, 2019). "Moreover, an increase of CRP, LBP, and Lf concentration (approximately 10-, 15-, and 30-fold, respectively) was observed during mastitis in cows." (PMID 30223561, 2018). "The potential targets of these high-frequency CMM in treating mastitis were intercellular adhesion molecule 1 (ICAM-1), interleukin-6 (IL-6), lipopolysaccharide binding protein (LBP), and lactotransferrin." (PMID 30911319, 2019). "The mRNA expression of genes responsible for the inflammatory response (TLR4, LBP, IL-1β, IL-6, IL-8, NF-κB and TNF-α) was significantly increased, consistent with the results of exogenous LPS-induced mastitis by infusion." (PMID 26893357, 2016). "Additionally, LBP also plays an important role in recognizing bacterial LPS and LTA during E. coli and S. aureus mastitis." (PMID 29283389, 2017).
Hepatic steatosis (10 papers, 2017 to 2025). Steatosis is a term used to denote lipid accumulation within hepatocytes. "The mechanisms of association between low LBP and fatty liver needs to be clarified and investigated in further studies with the larger sample size." (PMID 28107471, 2017). "Severe hepatic steatosis group had higher levels of LBP, isovaleric acid, propionic acid and lower levels of indoxyl sulfate and 3‐methylvaleric acid." (PMID 39494987, 2024). "In this study, LBP in HCV-infected subjects was only associated with ALT and fatty liver before and only with HbA1c and fatty liver after interferon-based therapy in multivariate linear regression analyses." (PMID 28107471, 2017). "This study provides a therapeutic target for fatty liver induced by LBP and suggests that antioxidative treatment strategies may be more effective than the use of phosphatidylcholine alone." (PMID 38615060, 2024). "Through the knockin of LBP, we obtained consistent animal phenotypes with the previous study, demonstrating that the binding of LBP to lipids entering LDs directly leads to the development of fatty liver." (PMID 38615060, 2024). "In the present study, LBP was identified as an independent predictor of the presence of liver steatosis, which may support the hypothesis that increased intestinal barrier permeability is one of the contributing factors to the development of liver steatosis." (PMID 41373509, 2025). "Participants with severe hepatic steatosis had significantly higher levels of all metabolic variables including HOMA‐IR, TG/HDL‐C ratio, TyG, TyG × BMI, TyG × WC, and VAI (all p < 0.01), higher levels of NHR, LBP, and a lower level of AST/ALT ratio." (PMID 39494987, 2024). "The negative correlation between LBP and 3‐methylvaleric acid was stronger in the severe hepatic steatosis group than in the non‐severe hepatic steatosis group." (PMID 39494987, 2024). "Interestingly, serum LBP level in HCV-infected subjects was related only to ALT and fatty liver before and only to HbA1c and fatty liver after the interferon-based therapy." (PMID 28107471, 2017). "Moreover, in HCV-infected subjects, the mean of LBP level was slightly lower in fatty liver group than that in non-fatty liver group (33.5±6.9 versus 36.1±7.7 μg/mL, p-value = 0.253)." (PMID 28107471, 2017). "Another limitation was that we could not examine the association between LBP and PNPLA3 polymorphisms, which might impact the degree of hepatic steatosis." (PMID 28216979, 2017).
steatosis (10 papers, 2017 to 2025). Increased lipid within the cytoplasm of cells. "In the study group, serum LBP level was positively associated with CAP values (Rho = 0.23, p = 0.02) and was significantly higher in advanced steatosis grade estimated by CAP (median 22.9 μg/mL in S1–S2 group vs. median 33.2 μg/mL in S3 group, p = 0.04)." (PMID 41373509, 2025). "Fasting led to significant TG accumulation and steatosis, which was consistent with the intraperitoneal injection of the LBP inducer LPS." (PMID 38615060, 2024). "As for intra-hepatocyte lipid accumulation, circulating LBP levels inversely correlated with the percentage of micro-vesicular steatosis (r = −0.38, p = 0.024)." (PMID 38139003, 2023). "PreM group showed a higher level of serum LBP, Ast and concentrations of hepatic triglyceride and total cholesterol, and developed liver macrovesicular steatosis." (PMID 35873168, 2022). "IL-6 is markedly up-regulated in steatotic livers, indicating a possible link among steatosis, IL-6, and LBP." (PMID 28216979, 2017). "As a known regulator of metabolism, continuous upregulation of LBP results in severe steatosis." (PMID 38615060, 2024). "Serum LBP was significantly higher in the steatosis grade 3 group as compared with the steatosis grade 1 or 2 groups and was positively correlated with steatosis score." (PMID 28216979, 2017). "First, we did not perform an analysis of the gut microbiome, serum LBP or LPS levels, other inflammation markers, and markers related to liver damage and steatosis, which could benefit from observing the underlying mechanism." (PMID 37744692, 2023). "Higher levels of LPS, as well as the LPS-binding protein (LBP), occurred in patients with NASH when compared to the patients with simple steatosis or healthy controls." (PMID 34948020, 2021). "Vitamin D deficiency deteriorated MASLD progression through the activation of toll-like receptor 2 (TLR2) and TLR4 through the CD14/human LPS-binding protein (LBP), subsequently triggering downstream inflammatory signaling molecules that result in steatosis and inflammation." (PMID 38732118, 2024). "Serum LBP concentration was significantly increased in NASH patients and was correlated with steatosis and ballooning scores, but not with the severity of lobular inflammation or fibrosis." (PMID 28216979, 2017). "In the present study, we were able to show that even in juvenile patients with beginning NAFLD e.g. in patients with simple steatosis grade 1 and no marked increase of ALT and AST, plasma endotoxin and LBP plasma levels are significantly higher than in controls." (PMID 28880885, 2017).
bacteremia (9 papers, 2010 to 2025). "In this study, we explored the clinical factors associated with bacteremia and plasma LBP, the latter of which is a marker of endotoxin-mediated inflammation." (PMID 31536546, 2019). "LBP is a secretory class 1 acute phase protein, previously associated with the response to bacterial sepsis." (PMID 28642677, 2017). "Due to its long half-life (2–3 days), LBP levels are detectable in serum for a long time after bacteremia, and it is a reliable marker of bacterial translocation." (PMID 40075763, 2025). "LBP is a 58 kDa glycoprotein produced by the liver and acts as a type I acute-phase molecule; its serum levels peak shortly after bacteremia onset and remain elevated for up to 72 h." (PMID 38139003, 2023). "LBP is an acute-phase protein produced in response to bacteremia." (PMID 40075763, 2025). "A recent meta-analysis of interventional studies found an association between modulation of dietary fiber content and serum LPS but not LBP concentrations; the detection of bacteremia was not even associated with LBP level in T2D patients in other studies." (PMID 38139003, 2023). "Moreover, serum lipopolysaccharide binding protein (LBP) remained unchanged even in DSS treated mice, indicating that DSS didn’t induce bacteremia in our study." (PMID 38521930, 2024). "The plasma LBP level was similar in patients with and without bacteremia." (PMID 31536546, 2019).
colitis (9 papers, 2013 to 2025). Inflammation of the colon. "Transcriptomic analysis showed that HTR2B agonist administration strengthened the beneficial effects of Trp in DSS-induced colitis mice with antibiotic exposure by reducing gut lipopolysaccharide-binding protein (LBP) production, IκB-α/nuclear factor-κB signaling, and M1 macrophage polarization." (PMID 39180723, 2024). "Mouse model with DSS-induced colitis displayed an extensive inflammatory state, manifested by a significant elevation of pro-inflammatory cytokines such as IL-6 in the blood, colon, and brain, and elevated LBP in the colon." (PMID 34806521, 2021). "Therefore, serum LBP was measured by ELISAs to assess bacterial translocation and colitis activity." (PMID 31632373, 2019). "In this study, RA supplementation significantly reduced serum I-FABP, LBP, and DAO levels in mice with DSS-induced colitis." (PMID 40777179, 2025). "In colitis mice, serum levels of DAO, LBP, and I-FABP were reduced following administration of VA, RA, or the combination." (PMID 40777179, 2025). "Indole treatment reduced LBP production and M1 macrophage polarization both in mice with DSS-induced colitis and in lipopolysaccharide-treated mouse macrophages; however, the HTR2B antagonist reversed the effects of indole." (PMID 39180723, 2024). "The reduction of LBP and the activation of HTR2B via indole reduce M1 macrophage polarization during colonic inflammation." (PMID 39180723, 2024). "Notably, treatment with the combination of CCFM1426 and VA also markedly decreased serum concentrations of I-FABP, LBP, and DAO in colitis mice, suggesting a protective effect on the intestinal barrier." (PMID 40777179, 2025). "Decreased serum concentration of OPG is typical for UC, as compared to CD and PSC-IBD, but while LBP was the strongest predictor of them all (AUC = 0.663), neither serum biomarker was capable to predict extent of colitis well." (PMID 31337064, 2019). "We also found these pro-inflammatory microbes were present in the colonic submucosa, and while we did not observe overt colitis prior to infection, we did find presence of serum LBP." (PMID 23405155, 2013).